CRP (C-reactive protein)
Diseases named in the same sentence as CRP in open-access papers (continued):
Sharing a sentence is not in itself a finding about the gene and the disease.
Impaired glucose tolerance (44 papers, 2007 to 2026). An abnormal resistance to glucose, i.e., a reduction in the ability to maintain glucose levels in the blood stream within normal limits following oral or intravenous administration of glucose. "Further, it has been shown that CRP levels are significantly increased in subjects with impaired glucose tolerance (IGT), and there is a strong association between increased hsCRP levels and IGT, implying that chronic inflammation is a risk factor for developing T2D." (PMID 40671150, 2025). "In patients with impaired glucose tolerance or T2D, pioglitazone reduced carotid IMT and atherosclerotic plaque inflammation in association with decreased CRP and increased HDL-cholesterol." (PMID 37200978, 2023). "Along with marked differences in adiposity measures, obese subjects also had higher prevalence of impaired glucose tolerance and T2D and thus higher HbA1c, higher mean arterial blood pressure, C-reactive protein, and triglycerides." (PMID 35798828, 2022). "The metabolic benefits of R-7050 were accompanied by reductions in fasting glucose, glucose tolerance impairment, plasma corticosterone, plasma free fatty acids, plasma CRP, as well as an increase in plasma levels of FGF-15." (PMID 34073455, 2021). "The neuroprotection caused by propranolol was accompanied by a reduction in fasting glucose, fasting insulin, glucose tolerance impairment, plasma CRP, plasma free fatty acids, plasma corticosterone, brain oxidative stress, and brain inflammation." (PMID 32492962, 2020). "The CRP-lowering effectivity of a diet enriched in oily fish, blueberries and wholegrain products was recently shown in patients with impaired glucose tolerance." (PMID 22472183, 2012). "In men and women, having lower HDL cholesterol, impaired glucose tolerance (IGT), and higher diastolic blood pressure were also associated with having a high CRP, while current smoking was associated with high CRP in men but not women." (PMID 21078191, 2010). "Elevated CRP levels are expected in any inflammatory or infectious processes, but extreme values of >150 mg/dl usually indicate a severe systemic inflammatory response and impaired glucose tolerance." (PMID 36327256, 2022). "The neuroprotection caused by propranolol was accompanied by a reduction in fasting glucose, fasting insulin, glucose tolerance impairment, plasma C-reactive protein, plasma free fatty acids, plasma corticosterone, brain oxidative stress, and brain inflammation." (PMID 32492962, 2020). "Positive association plasma MIF with impaired glucose tolerance and T2D independent of plasma CRP and IL-6." (PMID 26124760, 2015). "In logistic regression, non-deterioration of glucose metabolism was associated with disturbed glucose tolerance - impaired fasting glucose or impaired glucose tolerance - (p < 0.001) and CRP levels ≤ 0.04 mg/dL (p = 0.01), adjusted for age and anthropometric variables." (PMID 20673337, 2010). "It was observed that the administration of metformin for a long term, such as 12 months, decreases the level of C-reactive protein (CRP) in both women and men with impaired glucose tolerance." (PMID 39200267, 2024). "Nevertheless 7 subjects had detectable elevated CRP and 7 had elevated TNFα, all of whom reduced their levels post study, implying reduced inflammation associated with adiposity Three subjects did have impaired glucose tolerance (IGT) which normalized post-study independent of weight changes." (PMID 30785891, 2019). "For example, plasma levels of plasma CRP and ICAM levels are higher in diabetic subjects, and it is likely that increases in CRP levels also occur in patients with impaired glucose tolerance." (PMID 20847810, 2010). "Adjusted ( miR-155 was correlated to multiple metabolic and CADRF, including age, HTN, TC,HDL-C, LDL-C, Smoking, ACEI,statins, and CRP, but not sex, hereditary and DM or Impaired Glucose Tolerance." (PMID 28540143, 2017).
Impaired glucose tolerance (continued). "Lower HDL cholesterol, impaired glucose tolerance (IGT), and higher diastolic blood pressure were associated with having a high CRP in both men and women, while current smoking was associated with high CRP in men but not women." (PMID 21078191, 2010). "This is surprising since, although metformin did not decrease circulating levels of C reactive protein and cell adhesion molecules in subjects with impaired glucose tolerance, it reduced the TNFα-induced activation of NFκB and secretion of VCAM-1 and MCP-1 in vascular endothelial cells." (PMID 19317897, 2009). "A study comparing patients with impaired glucose tolerance (IGT) to non-diabetic subjects showed that IL-6, C-reactive protein (CRP), serum amyloid A protein, and fibrinogen were more elevated in patients with T2DM." (PMID 35401518, 2022).
endometriosis (43 papers, 2011 to 2026). The growth of functional endometrial tissue in anatomic sites outside the uterine body. "In terms of CRP levels, endometriosis was associated with an increase in this inflammatory marker in the control group compared to the healthy group." (PMID 40224541, 2025). "Univariable logistic regressions showed that among premenopausal women, current smoking, OCP use for 2–5 years and for 5–10 years, CRP level, and history of endometriosis demonstrated possible associations (p < 0.25) with CA125 levels ≥ 35 U/ml (N = 101)." (PMID 35568827, 2022). "The diagnostic performance of hsCRP was superior to the diagnostic performance of classical CRP to distinguish endometriosis from controls (especially stage III-IV during the luteal cycle phase)." (PMID 21827658, 2011). "The strength of this study lies in the fact that comparison of the diagnostic performance of hsCRP and CRP assays was evaluated on a large number of patients with laparoscopically confirmed or excluded endometriosis during all phases of the menstrual cycle." (PMID 21827658, 2011). "In this paper we compared the diagnostic performance of the hsCRP assay and the classical CRP assay to detect low grade inflammation in plasma of women with endometriosis." (PMID 21827658, 2011). "Diagnostic performance of hsCRP was superior to classical CRP in women with moderate-severe endometriosis." (PMID 21827658, 2011). "There might be an association of several factors linked to higher serum levels of CRP and infertility, particularly severe overweight, endometriosis or PCOS." (PMID 37361544, 2023). "For postmenopausal women (N = 1116), alcohol consumption of more than two drinks per day, caffeine intake, CRP, ferritin level, history of hysterectomy, oophorectomy, endometriosis, fibroids, and CAD demonstrated possible associations with CA125 concentration (p < 0.25) via linear regression models." (PMID 35568827, 2022). "The present study is aimed at finding out the association of inflammatory markers (C-reactive protein, fibrinogen, and homocysteine), proinflammatory cytokines (interleukin-17 and interleukin-33), and cardiovascular risk manifestation in females with endometriosis in comparison with the control." (PMID 34754275, 2021). "Our results, which covered three classes of molecules associated with systemic inflammation, namely oxylipins, immunomodulatory proteins and CRP, were largely similar with minimal differences at a level which precludes their use as diagnostic biomarkers for endometriosis." (PMID 27193963, 2016). "C-reactive protein was also elevated in women with endometriosis (median 0.10 mg/dL, IQR 0.04–0.32) compared with controls (0.085 mg/dL, IQR 0.03–0.21; p = 0.04)." (PMID 41590512, 2026). "For endometriosis, a dose of 50,000 IU of VD every 2 weeks for 12 weeks was found to reduce pelvic pain and lower C-reactive protein levels." (PMID 40076878, 2025). "The analysis of circulating inflammation parameters demonstrated significantly lower levels of IL-6, fibrinogen, and CRP in patients with endometriosis than in those with HGS-OC and other OC histotypes." (PMID 40723209, 2025). "Systemic inflammatory markers (IL-6, CRP, fibrinogen, hepcidin, ferritin, and ROS) were markedly lower in endometriosis, consistent with a localized inflammatory process." (PMID 40723209, 2025). "Numerous studies have been conducted to explore the correlation between endometriosis and CRP; however, this particular study stands out as the first to specifically investigate ruptured endometriosis." (PMID 37623476, 2023). "Given the inflammatory nature of endometriosis, several studies have delved into exploring the potential connection between CRP and this condition." (PMID 37623476, 2023). "Between stages III and IV of endometriosis, significant differences in concentrations of IL-6 (p = 0.040), hs-CRP (p = 0.007) and CA 125 (p < 0.001) were observed." (PMID 33669013, 2021).
endometriosis (continued). "In this study, women with endometriosis demonstrated a hypercoagulable and inflammatory state, manifested by elevated levels of CRP, homocysteine, and fibrinogen as well as IL-17 and IL-33." (PMID 34754275, 2021). "Proinflammatory cytokines such as IL-1, IL-6, and TNF-alpha stimulate the synthesis of CRP which are found to be overexpressed in women with endometriosis as compared to controls." (PMID 34754275, 2021). "CRP level was estimated to be 6.14 ± 0.35 mg/L in the control group, which elevated significantly (P < 0.001) by 72% in patients, whereas the level of CRP in the endometriosis group was 10.56 ± 0.39 mg/L." (PMID 34754275, 2021). "The endometriosis group in our study showed a significant increase in CRP levels as compared to the control, indicating increased CVD risk in these patients." (PMID 34754275, 2021). "Recently, one interesting study showed that CRP serum levels were significantly higher in patients affected by endometriosis than in healthy patients." (PMID 24567887, 2014). "The hsCRP assay was superior to the classical CRP assay for the detection of low CRP levels and for revealing subclinical inflammation in plasma of women with endometriosis." (PMID 21827658, 2011). "In our study the hsCRP assay was superior to the classical CRP assay for the detection of subclinical inflammation in plasma of endometriosis patients." (PMID 21827658, 2011). "Significantly increased CRP plasma levels were found in women with endometriosis when compared with controls when the hsCRP assay was used in samples obtained during the luteal phase (p = 0.008)." (PMID 21827658, 2011). "In conclusion, the hsCRP assay was superior to the classical CRP assay for the detection of low CRP levels indicating subclinical inflammation in plasma of endometriosis patients." (PMID 21827658, 2011). "Comparable plasma CRP levels between women with endometriosis and controls resulted in a low AUC (0.55) demonstrating limited clinical value." (PMID 21827658, 2011). "Using a similar cut-off value for CRP analyzed by the classical method, moderate-severe endometriosis was diagnosed with lower sensitivity (67.7%, p = 0.06) and comparable specificity (63.9%)." (PMID 21827658, 2011). "Significantly increased CRP plasma levels were found in women with endometriosis when compared to controls when the hsCRP assay was used in samples obtained during the luteal phase (p = 0.008), but not in samples obtained during follicular or menstrual phase." (PMID 21827658, 2011). "Plasma CRP and hsCRP levels were comparable in women with stage I-II of endometriosis and controls, resulting in low AUCs (0.50-0.57), that did not allow determination of any cut-off points, demonstrating no clinical value." (PMID 21827658, 2011). "Data regarding the CRP level in peripheral blood of endometriosis patients are relatively scarce and controversial probably related to differences in study design, patient selection and methodology used to detect CRP levels in peripheral blood." (PMID 21827658, 2011). "Do you use daily C reactive protein (CRP) after surgery for deep endometriosis?" (PMID 37742197, 2023). "Since endometriosis is considered an inflammatory disease, CRP could be an additional potential non-invasive biomarker of it, however, a non-specific one." (PMID 33669013, 2021). "Scarce data is available concerning the CRP level in the peripheral blood of endometriosis patients, which may be due to dissimilarity in patient selection, study design, and procedures applied to find out CRP levels." (PMID 34754275, 2021). "The inflammatory marker C-reactive protein (CRP) has been shown to be upregulated, especially when examined with a high sensitivity assay making it possible to detect subclinical inflammation in women with endometriosis." (PMID 26240814, 2015). "C-reactive protein (CRP) is an acute phase protein and a marker of inflammatory reaction, could serve as a potential non-invasive biomarker of endometriosis." (PMID 21827658, 2011).
endometriosis (continued). "We tested the hypothesis that a high sensitivity CRP assay (hsCRP) is more accurate than a classical CRP assay in the detection of subclinical inflammation in plasma of women with endometriosis." (PMID 21827658, 2011). "The CRP plasma levels were higher in women with stage III-IV of endometriosis than in women with stage I-II endometriosis or than in controls using either the classical CRP assay (p < 0.0001 or p < 0.0001, respectively) or the hsCRP assay (p < 0.0001 or p < 0.0001, respectively)." (PMID 21827658, 2011). "Comparison of our results with those from other studies reporting CRP levels in women with endometriosis is difficult due to differences in patient phenotype, patient number, type of peripheral blood (serum or plasma) and CRP methodology (variety of assays manufactured by a variety of companies)." (PMID 21827658, 2011). "In this study we demonstrated that CRP plasma concentrations within the normal reference range (between undetectable and 10 mg/L), as detected by the hsCRP assay, confirm the presence of subclinical inflammation in patients with endometriosis." (PMID 21827658, 2011). "The optimum cut-off value of plasma CRP > 0.71 mg/L obtained during the luteal phase of the menstrual cycle could predict nearly 13% more patients with moderate-severe endometriosis using the hsCRP assay when compared with the classical CRP assay." (PMID 21827658, 2011). "Furthermore, although women with endometriosis have greater odds of having elevated CRP levels than those without endometriosis, it is not a reliable biomarker, and other inflammatory conditions more commonly elevate CRP levels." (PMID 36652249, 2023). "CRP could be an additional potential biomarker in endometriosis." (PMID 34754275, 2021). "While we corrected for relevant confounders that were documented for the study population, i.e. BMI, endometriosis and smoking, other factors may have contributed to not finding an association between CRP and TFI." (PMID 31858023, 2019). "When analysed separately for patients who did not have a chronic disease that might cause elevated CRP levels (n = 56), the association remained non-significant in both the unadjusted analysis and the analyses adjusted for BMI, endometriosis and smoking." (PMID 31858023, 2019). "According to these evidences, endometriosis is now considered a chronic inflammatory disease, with inflammation not limited to peritoneal cavity but spread to systemic level, as signaled by elevated serum levels of markers as Ca-125 and C-reactive protein (CRP)." (PMID 24804204, 2014). "Indeed the AUC was significantly higher after hsCRP analysis than after classical CRP analysis for the diagnosis of moderate-severe endometriosis in combined analysis (all cycle phases combined) and for minimal-severe endometriosis (during the luteal phase of the cycle only)." (PMID 21827658, 2011). "However, CRP concentrations within the normal adult reference range provide valuable information of chronic inflammatory processes like Helicobacter pylori and Chlamydia pneumonia and also endometriosis, as demonstrated in our study." (PMID 21827658, 2011). "Comparison of the CRP plasma levels between the classical CRP assay and the hsCRP assay showed a good Spearman correlation coefficient, ranging between 0.74 and 0.997, which was significantly higher (p < 0.001) in the endometriosis group (0.996) than in the control group (0.74)." (PMID 21827658, 2011). "C-reactive protein (CRP), a marker of inflammation, could serve as a biomarker of endometriosis." (PMID 21827658, 2011). "Therefore, we tested the hypothesis that in plasma a high sensitivity CRP assay (hsCRP assay) is more accurate than a classical CRP assay (classical CRP) to detect low grade inflammation in plasma of women with endometriosis." (PMID 21827658, 2011).